BRCA1 (BRCA1 DNA repair associated)
Diseases named in the same sentence as BRCA1 in open-access papers (continued):
Sharing a sentence is not in itself a finding about the gene and the disease.
ovarian carcinoma (continued). "In addition, a study found that CpG island methylation in ovarian cancer is related to the silencing of many genes, including BRCA1, RASSF1A, LOT1 and Hmlh1; the silencing of these genes may be involved in the development of ovarian cancer." (PMID 30079293, 2018). "This held true in the Phase III NOVA trial, in which patients with platinum‐sensitive recurrent ovarian cancer receiving niraparib (a PARPi) maintenance therapy had increased progression‐free survival (PFS) compared to placebo control, irrespective of BRCA1/2 mutational or HR deficiency status." (PMID 30467127, 2018). "The NCCN and the Society of Gynecologic Oncology both recommend BRCA1 and BRCA2 genetic testing for all women with ovarian cancer, and parallel re-testing of all of these women using multi-gene panels may be warranted due to the observed mutation rates in this group." (PMID 28281021, 2017). "In our cohort, bias for a high rate of BRCA1 promoter methylation might be the selection of exclusively high-grade histology as well as 100% relapsed ovarian carcinomas, also single centre selection bias cannot be ruled out." (PMID 29137324, 2017). "Based on data available for families eligible for BRCA1/BRCA2 testing in the Swedish cancer registry, Bermejo and Hemminiki found that GC before the age of 70 was twice as frequent (RR 2.04; 95 % CI 1.14–3.12) in families with breast and ovarian cancer than in the general population." (PMID 26779294, 2016). "In accordance, low BRCA1 mRNA expression in ovarian cancer cell lines resulted in decreased and increased apoptotic response to PTX and platinum respectively and PTX-sensitive human brain and neck squamous cell carcinoma (HNSCC) with acquired cisplatin resistance had high expression of BRCA1." (PMID 26900348, 2016). "Germline BRCA1/2 status is not only relevant to women with ovarian cancer but also to women without cancer, who may be at an increased risk of developing the disease and could therefore benefit from prevention strategies." (PMID 27242959, 2016). "Women harbouring BRCA1/2 mutations demonstrate a 30–40-fold increased risk of high-grade serous extra-uterine Müllerian cancers (HGSEMC), otherwise referred to as ‘ovarian carcinomas', which frequently develop from fimbrial cells but not from the proximal portion of the fallopian tube." (PMID 27216078, 2016). "Brazilian inhabitants may have peculiar genetic characteristics associated with ethnic diversity, and studies focusing on the entire BRCA1/BRCA2 gene sequencing in Brazilian ovarian cancer patients are still lacking." (PMID 27914478, 2016). "Logistic regression modeling demonstrated a relationship between elevated NUAK1 expression and aggressive clinic-pathologic features, as well as select molecular subtypes in ovarian cancer patients, but not with BRCA1/2 status [odds ratio (OR) = 0.93, p > 0.05]." (PMID 27833898, 2016). "Of note, none of the germline BRCA1/2 had a family history of breast and ovarian cancer." (PMID 27907908, 2016). "Wild Type BRCA1 but not the disease associated mutants have been shown to bind in vitro to SUMO E2 conjugating enzyme Ubc9 and this is responsible for both ER-alpha activation and tumor suppression of breast and ovarian cancer cells." (PMID 28164176, 2016). "The frequency of this mutation is unknown, however no other mutation carriers were reported in a BRCA1/BRCA2 mutation screen of 136 breast and/or ovarian cancer families of French Canadian descendent." (PMID 26622941, 2015). "Our work sought to identify miRNAs that could predict the prognosis of ovarian cancer patients who had no alterations in BRCA1/2 and had initially been treated with a platinum-based chemotherapy regimen." (PMID 25537514, 2015).
ovarian carcinoma (continued). "Finally, detailed family history was available only in 60 % (n = 12/20) of BRCA1/2 positive patients, of whom in five individuals it was negative for breast/ovarian cancer in first and second degree relatives (41 %)." (PMID 25366421, 2015). "In addition, it is also known that 9–14 % of nonmutated ovarian cancers bear an epigenetic silencing of the BRCA1 gene due to promoter hypermethylation." (PMID 26109557, 2015). "In summary, our work identified that some BRCA1/2 alteration non-carriers benefit from platinum-based chemotherapy, a finding that has potentially important implications for the clinical management of patients with ovarian cancer." (PMID 25537514, 2015). "The majority of ovarian cancers are not attributed to hereditary germlinemutations in the BRCA1 and 2 genes, so a key question is whether single-agentPARP inhibitors can be used to treat patients within the larger ovarian cancerpopulation." (PMID 26669452, 2015). "Several studies have demonstrated that, due to variations in splice sites, BRCA1/BRCA2 may generate truncated, non-functional proteins that may be associated with a predisposition to breast and ovarian cancer." (PMID 25683334, 2015). "Ovarian cancer patients carrying alterations (i.e., germline mutations, somatic mutations, hypermethylations and/or deletions) of BRCA1 or BRCA2 (BRCA1/2) have a better prognosis than BRCA1/2 alteration non-carriers." (PMID 25537514, 2015). "Indeed, in ovarian cancer cell lines WRAP53β rapidly accumulates at DNA breaks, where it orchestrates the accumulation of DNA repair proteins involved in both HR and NHEJ, including RNF168, 53BP1, BRCA1 and RAD51." (PMID 26426684, 2015). "Therefore, the defects in this conserved BRCA1-dependent RNAP II cleavage and degradation pathway may be critical for the initiation of breast and/or ovarian cancer." (PMID 26418880, 2015). "In this study, no separate effect of BRCA1 mutation status on overall prognosis of TNBC was evaluated, negative ER and PR status was defined as nuclear staining of ≤10% and patients with previous ovarian cancer were included in the study." (PMID 24348864, 2014). "Despite the early success of PARP inhibitors in demonstrating efficacy and a favorable toxicity profile in the treatment of previously heavily treated hereditary BRCA1/2-related breast and ovarian cancers, trials that expanded to include patients without BRCA1/2 mutations were less successful." (PMID 25093514, 2014). "Notably, BRCA1 activation was an effective way to induce AGTR1 expression in primary ovarian cancer cells and a positive correlation exists between BRCA1 and AGTR1 expression in human ovarian cancer specimens." (PMID 24321324, 2013). "However, no significant BRCA1 expression differences (P > 0.05) were observed in ovarian cancer with an unmethylated BRCA1 promoter (P > 0.05) compared with adjacent normal tissue." (PMID 24321281, 2013). "However, the crosstalk between BRCA1 and EGFR signaling pathways in ovarian cancer remains largely unknown." (PMID 24321281, 2013). "Clarifying the complex interactions between BRCA1 and EGFR signaling pathways at the transcriptional, posttranscriptional, and epigenetic levels may improve our understanding of the basic molecular mechanism of ovarian cancer." (PMID 24321281, 2013). "Moreover, a clinical-epidemiologic study suggests that mutations mapping to the C-terminal region of BRCA1, which would be predicted to disrupt BRCA1 function in HDR, do not abrogate the ability of BRCA1 to suppress ovarian cancer." (PMID 23802008, 2013). "Moreover, a significant fraction of sporadic (non-hereditary) breast and ovarian cancers exhibit reduced or absent expression of the BRCA1 protein, suggesting an additional role for BRCA1 in sporadic cancers." (PMID 23802008, 2013). "However, no significant BRCA1 expression differences were observed in ovarian cancer with unmethylated BRCA1 promoter as compared to adjacent normal tissue (Figure 3Aiii and Ci, P > 0.05)." (PMID 24321324, 2013).
ovarian carcinoma (continued). "BRCA1 may induce its cytoprotective effect via modulating the expression of both SMAD6 and FST, and in turn, may induce BMP signaling pathways, which may then inhibit or delay the progression of ovarian cancer, specifically epithelial-origin ovarian cancer." (PMID 22685544, 2012). "BRCA1 is also expressed at variable levels in a wide range of normal and pathological human tissues, but mostly it was investigated in relation to tumor suppression in breast, prostate and ovarian cancer." (PMID 22685544, 2012). "Finally, additional studies specifically examining the interplay between BRCA1 and FST and its effect(s) on cellular processes may be helpful in devising targeted treatment for human ovarian cancer." (PMID 22685544, 2012). "SNU251 ovarian cancer cell line carrying truncation of 49 C-terminal aminoacids of the BRCA1 gene (partial deletion of 2nd BRCT domain) demonstrated increased sensitivity to paclitaxel in a cell viability assay; this effect was reversed by the introduction of the wild-type BRCA1." (PMID 21819606, 2011). "Notably, we also found that PARP inhibitors, which have shown unprecedented activity against ovarian tumors and other tumors that have mutated BRCA1 and BRCA2, remarkably sensitized ovarian cancer cells to FdUrd but not 5-FU." (PMID 22194930, 2011). "Hereditary breast and ovarian cancer susceptibility gene product BRCA1 has been shown to serve as a positive regulator of SIRT1 expression by binding to the promoter region of SIRT1, but cross talk between BRCA1 and TFII-I has not been investigated to date." (PMID 21407215, 2011). "However, as BRCA1 and BRCA2 cancers comprise only 5 to 10% of all cancers and potential controls were excluded if a family history of breast or ovarian cancer was noted in the medical record, it seems very unlikely that more than a few of the 'control' cases had germline BRCA1 mutations." (PMID 20149218, 2010). "However, surprisingly, no ovarian cancers occurred in BRCA1/2 carriers, even though 21 women have lived beyond 40 years of age without an oophorectomy." (PMID 20234365, 2010). "This suggests that inactivation of the PALB2 gene may cause similar biological and phenotypic changes as inactivation of the BRCA1 or BRCA2 genes; the latter is responsible for a fraction of breast and ovarian cancers, and a dysfunction of BRCA2 alone - for the Fanconi anemia (FA) syndrome." (PMID 20122277, 2010). "Nevertheless, almost all investigators agree that neither lack of family history nor late disease onset are reliable indicators of BRCA1 wild-type status in OC patients, therefore DNA testing of non-selected ovarian cancer cases is recommended by some laboratories." (PMID 19338682, 2009). "In addition, literature data on the occurrence of BRCA1, BRCA2, CHEK2 and NBS1 mutations in non-selected ovarian cancer patients were reviewed." (PMID 19338682, 2009). "Defects in this conserved BRCA1-dependent RNAPII cleavage and degradation pathway may be critical for the initiation of breast or ovarian cancer, predicting that genetic defects in other conserved components of this pathway may also contribute to these diseases." (PMID 18197258, 2008). "Thus, BRCA1 expression is decreased or absent in a significant proportion of sporadic breast and ovarian cancer cases, in part because of hypermethylation of the BRCA1 promoter on CpG islands." (PMID 16434996, 2006). "The I1307K allele was equally distributed among women with sporadic (17/382; 4.6%) and inherited (10/143; 7%) breast and/or ovarian cancer irrespective of their being diagnosed before or after 42 years of age and among asymptomatic (7/53; 13.2%) and cancer manifesting BRCA1/2 carriers (10/143; 7%)." (PMID 10901363, 2000).
ovarian carcinoma (continued). "There was some evidence for a nonbreast/ovarian cancer risk difference by age at first BC diagnosis in noncarriers (under 45 years: SIR, 1.68 [95% CI, 1.39 to 2.01]; 45 years or over: SIR, 1.15 [95% CI, 1.02 to 1.28]), which we did not observe for BRCA1/BRCA2 PV carriers." (PMID 39475295, 2025). "However, unlike the BRCA1 and BRCA2 genes, which have clustered regions associated with breast and ovarian cancers, no clear hotspot could be identified in BARD1." (PMID 40805222, 2025). "The limitations are the underestimation of the frequency of carriers in families with ovarian cancer and in families with prostate cancer, the non-applicability to ethnic minorities, the impossibility of incorporating third-degree relatives, and non-inclusion of other genes besides BRCA1/BRCA2." (PMID 38672070, 2024). "Comparative analysis of the difference in ovarian cancer mutation genes between the BRCA1/2 mutation group and the non-mutation group uncovered that FAM175A, EMSY, PTCH1, and HNF1B were significantly highly mutated in the group without BRCA1/2 mutations, particularly PTCH1: c.3907C>T (p.R1303C)." (PMID 38817903, 2024). "However, this study utilized a panel consisting of BRCA1/2, PALB2, CHEK2, and ATM only, whereas the GRACE panel was more extensive and included genes not traditionally associated with ovarian cancer, which explains our higher prevalence of P/LP variants overall." (PMID 39061202, 2024). "Interestingly, responses were observed in two patients with monoallelic BRCA1/2-altered tumors (HNSCC and melanoma) that are not part of the canonical spectrum of BRCA1/2-associated cancers (hereditary breast, pancreatic, prostate and ovarian cancers)." (PMID 37277454, 2023). "While screening for ovarian cancer has not been shown to improve outcomes, risk-reducing bilateral salpingo-oophorectomy (RRSO) is the most efficient prophylactic strategy proposed by international guidelines for ovarian cancer prevention in BRCA1\2 mutation carriers." (PMID 36614207, 2023). "We hypothesize that postponement of oophorectomy after salpingectomy, to the age of 40–45 (BRCA1) or 45–50 (BRCA2) years, compared with the current standard salpingo-oophorectomy at age 35–40 (BRCA1) or 40–45 (BRCA2) years, is non-inferior in regard to tubo-ovarian cancer risk." (PMID 37045546, 2023). "Moreover, we cannot neglect the fact that a respectable percentage of breast and ovarian cancer patients, with inherited BRCA1/2 genetic alterations, do not have a clear family history, due to a small family structure, the predominance of males in the family, and paternal inheritance." (PMID 35986351, 2022). "Therefore, targeting BRCA1 and BRCA2 may reverse acquired resistance in ovarian cancer." (PMID 36551731, 2022). "Although germline BRCA1 and BRCA2 (BRCA1/2) pathogenic variants account for a large proportion of Hereditary Breast and Ovarian Cancer (HBOC), a Scottish study on BRCA1/2 testing in ovarian cancer revealed that 48% of pathogenic variants did not fulfil family history criteria for testing." (PMID 35190596, 2022). "Thus, measuring the levels of BRCA1 and BRCA2 mRNAs in ovarian cancers using either the NanoString nCounter system or ddPCR may help predict which patients will benefit the most from platinum-based chemotherapy and PARPi when DNA tests are negative or inconclusive." (PMID 35203410, 2022). "Moreover, in our cohort 6% of our TNBC/HGSC cases harbored a germline genetic alteration in BRCA1/2 genes which indicate that a respectable percentage of non-familial breast and ovarian cancer may harbor a BRCA pathogenetic germline alteration." (PMID 35986351, 2022). "After BRCA1-2 analysis, PVs in other cancer susceptibility genes were searched and classified according to whether they were traditionally associated (canonical HBOC genes) or not (candidate non-canonical HBOC genes) to breast and ovarian cancer." (PMID 34026625, 2021).
ovarian carcinoma (continued). "A phase III study on patients with platinum-sensitive recurrent ovarian cancer taking PARP inhibitors as maintenance therapy found that these patients had longer progression-free survival compared with the placebo group, independent of the BRCA1/2 mutation status or other HR repair gene status." (PMID 34712221, 2021). "However, the immunogenicity of BRCA1/2 mutation-associated ovarian cancers does not exhibit improved responses to ICI, most likely because of the overall low TMB, and carry a limited predictive value in ovarian cancer." (PMID 34712221, 2021). "Notably, AZD compounds did not change the mRNA expression of BRCA1/BRCA2 in ovarian cancer cells; however, AZD8835 could downregulate BRCA1/BRCA2 mRNA in KRAS-mutated OVCAR-8 cell via ERK signaling." (PMID 32194423, 2020). "No cases of ovarian cancer had been found in the III generation female in this family, but genetic tests have shown that there were 1342A>C single mutations in the BRCA2 gene in III2, III4, and III7, and there were two mutations of BRCA1 (3326A>T) and BRCA2 (1342A>C) in III8." (PMID 32356124, 2020). "In addition, BRCA1/2 are tested in breast and ovarian cancers, but it is not obligatory." (PMID 31787752, 2020). "Case analysis of the likely pathogenic reclassified VUS variant BRCA1 p.V1653L (rs80357261) by MH BRCA revealed in our cohort three breast and/or ovarian cancer patients with otherwise no additional pathogenic event in the germline samples, which might be indicative for the disease-causing event." (PMID 32486089, 2020). "However, the contribution and the frequency of BRCA1 mutations in individuals with TNBC, not specifically selected for age at diagnosis or enriched family history of breast/ovarian cancer, are not investigated in the Tunisian population and are to be established." (PMID 30975216, 2019). "However, the contribution and the frequency of BRCA1 mutations in individuals with TNBC, not specifically selected for age at diagnosis or enriched family history of breast/ovarian cancer, have not been investigated in the Tunisian population and are to be established." (PMID 30975216, 2019). "However, unlike that of BRCA1/2 mutations, the functional role of these ADAMTS mutations in ovarian cancer cells is largely unknown." (PMID 29179445, 2017). "Although the decrease in BRCA1 activity upon Cdk1 inhibition was not prominent for combined treatment of RO-3360 and Cisplatin, it is certain that the inhibition of Cdk1 was significantly suppressed cell growth and promoted apoptosis of ovarian cancer cell lines treated with cisplatin." (PMID 27385216, 2016). "Patients with BRCA1 mutations were enriched for a family history of breast (5/23 (21.7%)) and ovarian cancers (2/23 (8.7%)), whereas patient cases with BRCA2 mutations were enriched for a family history of breast (7/17 (41.2%)) but none of the family members had ovarian cancers." (PMID 29263802, 2016). "For ovarian cancer, LOF mutations were not enriched in hGIS1 genes (P=0.87) but were enriched in hGIS2 genes (P<0.0001); this increase in significance was due to the presence BRCA1 and BRCA2 in the hGIS2 gene list, which accounted for 70% of the LOF mutations in hGIS2 genes." (PMID 27071721, 2016). "Women with a BRCA1 or BRCA2 mutation who have not chosen prophylactic salpingo-oophorectomy may follow determination of Ca125 and transvaginal ultrasound since age 35 (IIC), but they should be informed that early detection of ovarian cancer is not guaranteed." (PMID 26669313, 2015). "As our study was limited by the inability to perform a comprehensive screen of both BRCA1 and BRCA2 due to cost limitations and the use of banked samples rather than a series, the overall frequency of mutation carriers in ovarian cancer cases not selected for cancer family history remains unknown." (PMID 25884701, 2015).